EGFR (epidermal growth factor receptor)
Diseases named in the same sentence as EGFR in open-access papers (continued):
Sharing a sentence is not in itself a finding about the gene and the disease.
lung adenocarcinoma (continued). "Taken together, these data showed AK4-AK1 consensus gene signature has significant impact on the survival of lung adenocarcinoma patients and may represent an important signaling axis that affect the pathogenesis of lung adenocarcinomas and the response to EGFR inhibition." (PMID 31444368, 2019). "Thus, when the specimens of primary lesions are not available in patients with advanced lung adenocarcinoma, the EGFR mutation status of metastatic lesions can be analyzed to represent the primary lesions for guiding the treatment." (PMID 31174617, 2019). "Therefore, the purpose of our study was to identify the imaging markers that reflect the EGFR mutation status by comparing CT imaging-based histogram features between bone metastases with and without EGFR mutation in patients with primary lung adenocarcinoma." (PMID 31174617, 2019). "The proposed deep learning system predicts EGFR‐mutant of lung adenocarcinomas in CT images noninvasively and automatically, indicating its potential to help clinical decision‐making by identifying eligible patients of pulmonary adenocarcinoma for EGFR‐targeted therapy." (PMID 31074592, 2019). "Although PD1 blockade combined with VEGF blockade and chemotherapy significantly improved PFS and OS among patients with lung adenocarcinomas with EGFR mutations, whether or not one subtype benefits more than the other remains un-known." (PMID 31722672, 2019). "Although the current clinical practice guideline classifies lung adenocarcinoma patients with EGFR del19 and L858R in the same group, our data along with above evidence indicates that these two subtypes may be different not only in biology, but also in immunogenicity." (PMID 31722672, 2019). "CT imaging-based histogram features of bone metastases with and without EGFR mutation in patients with primary lung adenocarcinoma were identified, and they may contribute to diagnosis and prediction of EGFR mutation status." (PMID 31174617, 2019). "Lung adenocarcinoma with EGFR mutation shows strong association with female non-smokers." (PMID 31531095, 2019). "A negative relationship was shown in the lung adenocarcinoma tissues with EGFR mutations (n = 102)." (PMID 31801598, 2019). "Though, VEGFR2 shares with EGFR key intracellular partners such as SHC1, protein tyrosine kinase 2, and phospholipase C. EGFR-mutant lung adenocarcinoma patients who acquired EGFR-TKI treatment resistance may benefit from blocking VEGFR2 related angiogenesis and tumor growth." (PMID 31570733, 2019). "In addition, GGO volume percentages were significantly higher in patients with primary lung adenocarcinomas with EGFR mutation than in adenocarcinomas without EGFR mutation." (PMID 30956990, 2019). "Therefore, the present study aims to investigate the frequency of EGFR and KRAS mutations in a large Brazilian series of lung adenocarcinoma, and to correlate the presence of these mutations with patients’ genetic ancestry and clinicopathological and sociodemographic characteristics." (PMID 30824880, 2019). "Therefore, it’s prudent to develop effective and safe drugs targeting EGFR in lung adenocarcinoma." (PMID 29892225, 2018). "Afatinib may be the optimal EGFR-TKI in patients with advanced lung adenocarcinoma harboring EGFR-activating mutation, particularly in the absence of BM." (PMID 29849936, 2018). "Our study suggest that, different from it in usual lung adenocarcinoma, EGFR tyrosine kinase inhibitor used in primary PEACs might be unreasonable and inefficient, but these patients might have greater possibility to benefit from checkpoint blockade immunotherapy." (PMID 29587865, 2018).
lung adenocarcinoma (continued). "However, since genetic testing-based therapy was put into the guidelines for treating advanced lung adenocarcinoma, the challenge lies in the availability of rebiopsy tissues from patients who failed to respond to treatment with first or second-generation EGFR-TKIs." (PMID 30444875, 2018). "Therefore, an EGFR pathway could be activated more constantly than in EGFR-TKI–sensitive lung adenocarcinoma cells." (PMID 29463039, 2018). "Afatinib may be the optimal EGFR-TKI for advanced lung adenocarcinoma harboring EGFR-activating mutations, particularly in the absence of BM." (PMID 29849936, 2018). "However, its role in EGFR-mutated lung adenocarcinoma, especially to EGFR-tyrosine kinase inhibitor (EGFR-TKI) is not clear." (PMID 29484139, 2018). "Moreover, carcinoembryonic antigen levels were reported to be independently prognostic in lung adenocarcinoma patients without EGFR mutations." (PMID 29849818, 2018). "Whether or not they are associated with EGFR mutations is also controversial; they might be related to different races and different stages of lung adenocarcinoma." (PMID 28988295, 2018). "The prognosis of patients with epidermal growth factor receptor (EGFR) mutant adenocarcinoma of the lung (Mt) and EGFR wild-type adenocarcinoma (Wt) after complete resection of the lung differ; however, the mechanisms responsible for these differences remain unclear." (PMID 30290774, 2018). "In addition, our data indicate that lung adenocarcinoma patients with high numbers of oncogenic gene alterations may show the worst responses to EGFR-TKI targeted therapy." (PMID 29343775, 2018). "Consequently, whether erlotinib is superior to gefitinib in the treatment of young patients with brain metastases following EGFR-mutant lung adenocarcinoma, a prospective randomized controlled study of larger samples is required for clarification." (PMID 30458751, 2018). "Another study suggested that circulating miR-122 and miR-195 may have prognostic significance in predicting EGFR mutation status and overall survival in female, non-smoking lung adenocarcinoma patients." (PMID 28496005, 2017). "Given that we found a rare EGFRT790M subclone in the polyclonal resistant tumor, we next explored whether BRAFV600E expression could promote resistance to EGFR TKI treatment in H1975 human lung adenocarcinoma cells that endogenously express EGFRT790M and EGFRL858R." (PMID 28287179, 2017). "Single gene assays, which may be sufficient for treatment prediction today, may be of limited use in the differential diagnostics of synchronous tumour vs. intrapulmonary metastasis as most lung adenocarcinomas are not EGFR mutated." (PMID 28347348, 2017). "The EGFR mutation rate in patients without adenocarcinoma of the lung is <5%." (PMID 29050314, 2017). "Thus, erlotinib therapy acted as a selective pressure for the evolution of multiple concurrent clonal and subclonal genetic alterations that could cooperate to drive rapid drug-resistant disease progression in EGFR-mutant lung adenocarcinoma." (PMID 28287179, 2017). "Interestingly, no mutations were identified in EGFR gene that together with KRAS is the most commonly mutated gene in lung adenocarcinoma." (PMID 28194229, 2017). "However, as far as we were concerned, this study represents the first comparison study between MPP-positive adenocarcinoma and MPP-negative adenocarcinoma in EGFR exon 19 and 21 mutations of TNM stage III lung adenocarcinoma with regard to clinicopathologic characteristics and prognosis." (PMID 28380449, 2017). "Therefore, our finding of smoking and EGFR mutation associated miRNA signature (miR-23a-3p, miR-223-3p and miR-451a) shed light on their biological importance in EGFR signaling pathway in lung adenocarcinoma development and progression affected by smoking habit." (PMID 29383112, 2017).
lung adenocarcinoma (continued). "However, survival analysis of only lung adenocarcinoma patients with EGFR-non-mutated status identified poorer overall survival (statistically significant at p≤0.005) with higher MEOX2 and GLI-1 protein co-expression levels (p=0.045 and p=0.006, respectively)." (PMID 28978016, 2017). "All together, our study indicates that the EGFR T790M mutation may not be associated with clinical outcomes of first-generation EGFR-TKI re-challenge for EGFR-mutant advanced lung adenocarcinoma patients." (PMID 27999211, 2017). "The aim of our study was to analyze the mutational rate of EGFR, KRAS, BRAF, ERBB2 and PI3KCA in a large cohort of 2,219 unselected French patients presenting in routine clinical practice for first line treatment decision of metastatic or recurrent lung adenocarcinoma." (PMID 28881604, 2017). "For male patients with grade II–III and III lung adenocarcinoma, although there was a numerical difference in the incidence of EGFR mutations (20.0% for Asians and 7.1% for non-Asians), the number of patients was small and we did not detect a statistical significance (p = 0.28)." (PMID 29232915, 2017). "In conclusion, PIK3CA mutation may not be associated with primary resistance to EGFR TKI among lung adenocarcinoma patients." (PMID 27734950, 2016). "Whether the co-existing PIK3CA mutations cause primary resistance to EGFR TKI in lung adenocarcinoma was still not well studied." (PMID 27734950, 2016). "We recruited 1004 consecutive patients with lung adenocarcinomas regardless of initial stage and treatments, and tumor samples such as biopsy, surgical, or cytologic specimens were included if sufficient tissue were available for EGFR mutational analysis." (PMID 27861565, 2016). "Similarly, activating mutations in EGFR are common in lung adenocarcinomas, but they are typically not present in squamous cell carcinomas." (PMID 27220886, 2016). "As a consequence, ERBB2 CNA may be a valuable biomarker of prognosis in lung adenocarcinoma patients without EGFR-activating mutations." (PMID 26824984, 2016). "Notably, 17% of KRAS mutant lung adenocarcinomas harbour the G12D substitution (glycine to aspartic acid at position 12) which confers a more invasive tumour phenotype and a reduced response to anti-EGFR targeted therapies." (PMID 27933110, 2016). "Findings from previous studies reporting the relationship between EGFR mutations and initial stage were limited to selected populations such as patients with surgically resected or advanced lung adenocarcinomas, and screening was not considered as a confounding factor." (PMID 27861565, 2016). "Furthermore, in our analysis, among lung adenocarcinoma patients with detailed smoking and EGFR mutation status, there was an even higher rate of never-smokers (64.8%)." (PMID 27191886, 2016). "In conclusion, PIK3CA mutation may not be associated with primary resistance to EGFR TKI in lung adenocarcinoma patients." (PMID 27734950, 2016). "Therefore, the 1st-line treatment to patients with mutant EGFR advanced lung adenocarcinoma is an important issue whether chemotherapy or EGFR-TKIs selected." (PMID 26609535, 2015). "Our results suggest that GAS5 in combination with gefitinib inhibited EGFR activity and the phosphorylation of its downstream pathway components, which is important to overcome resistance, and, finally, restored the sensitivity of lung adenocarcinoma cell lines to the EGFR-TKIs." (PMID 25925741, 2015). "However, the biological role of GAS5 and its function in EGFR-TKI-resistant lung adenocarcinoma remain largely unknown." (PMID 25925741, 2015). "However, several retrospective studies in resectable and advanced lung adenocarcinoma have suggested that gender was not an independent factor for EGFR mutation." (PMID 26599344, 2015). "EGFR mutations tend to occur in lung adenocarcinomas from female non-smokers." (PMID 26556242, 2015).
lung adenocarcinoma (continued). "In addition, although mut-EGFR is not frequent in solid predominant lung adenocarcinoma, EGFR-mutated adenocarcinomas with solid subtype have poor response to EGFR TKIs." (PMID 26422230, 2015). "In an exploratory analysis, the protein and mRNA expression levels of DGKa, PDE4A and PDE4D were examined in the five EGFR-mutant lung adenocarcinoma cell lines in an effort to explore whether DGKa regulates MTOR transcription through modulation of cAMP levels." (PMID 26639561, 2015). "Furthermore, patients are enrolled unselected: patients with EGFR wild-type and patients with EGFR mutations, lung adenocarcinoma and non-adenocarcinoma are all included." (PMID 26285137, 2015). "Therefore, we hypothesized that GAS5 may also mediate IGF-1R function to enhance the sensitivity to EGFR-TKIs in lung adenocarcinoma." (PMID 25925741, 2015). "Interestingly, although somatic mutation is rare in EGFR/KRAS/ALK-negative lung adenocarcinoma of never-smokers, the PCDHB14 (cell adhesion) Y670S mutation and YTHDF1 (RNA binding) I492V mutations were each found in two cases (12.5%)." (PMID 24576404, 2014). "However, the relationship between the EGFR mutation and the subtype of the new lung adenocarcinoma classification is not clear." (PMID 24885205, 2014). "Circulating miR-195 and miR-122 may have prognostic values in predicting the overall survival as well as predicting EGFR mutation status in non-smoking female patients with lung adenocarcinoma." (PMID 24282590, 2013). "However, in the present study, no gender differences were observed in the characteristics of the EGFR- or KRAS-mutated lung adenocarcinomas other than tumor size, indicating that smoking status has a greater effect on the cause of lung adenocarcinoma than gender differences in Japanese patients." (PMID 24179496, 2013). "We investigated the relationship between miR-122 and EGFR mutation status along with survival in non-smoking female lung adenocarcinoma, and found that reduced expression of miR-122 in plasma was associated with EGFR mutation and favorable survival, especially in patients with advanced disease." (PMID 24282590, 2013). "The results of our study provided some evidence that plasma levels of miR-195 and miR-122 expression were associated with EGFR status along with overall survival of non-smoking female lung adenocarcinoma patients, especially in those with advanced stage or EGFR mutation positive." (PMID 24282590, 2013). "However, only the association with EGFR mutation was replicated in the TCGA data, suggesting loss of DOK2 is associated with EGFR mutation but not KRAS mutation in human lung adenocarcinoma." (PMID 24255704, 2013). "High expression of miR-195 and miR-122 in plasma could help predict EGFR mutation status and overall survival of advanced stage female non-smokers with lung adenocarcinoma." (PMID 24282590, 2013). "On the other hand, there is a report suggesting that no intratumor heterogeneity of EGFR expression is found in mutant EGFR lung adenocarcinomas, and also that no disparity is found between the EGFR mutation status of the primary tumor and lymph node metastasis." (PMID 23879483, 2013). "miRNA expression and survival in non-smoking female lung adenocarcinoma by EGFR mutation status." (PMID 24282590, 2013). "Which indicated that miR-195 and miR-122 may possibly be potential non-invasive biomarker in EGFR mutation prediction and prognosis prediction of non-smoking female lung adenocarcinomas." (PMID 24282590, 2013). "Furthermore, the A431 cell line was not derived from a lung adenocarcinoma, has both wildtype EGFR and K-Ras alleles, and is exquisitely sensitive to EGFR inhibition." (PMID 17096850, 2006). "Therefore, alterations of these genes can independently occur in lung adenocarcinomas, unlike mutations of EGFR and K-ras." (PMID 16052218, 2005).
lung adenocarcinoma (continued). "We used a human lung adenocarcinoma cell line (A549) that was opsonized with cetuximab as a model for NK-mediated ADCC, because cetuximab is a hIgG1 anti-EGFR antibody capable of binding CD16a and enabling ADCC2." (PMID 41219228, 2025). "Focusing on the high-proportion subtype of lung adenocarcinoma (LUAD), research has found that Hes1 expression is significantly elevated in EGFR-TKI-resistant cells." (PMID 40755759, 2025). "Osimertinib, a third-generation, irreversible epidermal growth factor receptor tyrosine kinase inhibitor (EGFR TKI), remains the standard first-line systemic therapy for metastatic EGFR-mutant lung adenocarcinoma." (PMID 40256355, 2025). "The EGFR and ALK genes are also the primary gene targets for targeted therapy in lung adenocarcinoma." (PMID 41020204, 2025). "An analysis of The Cancer Genome Atlas Lung Adenocarcinoma (TCGA-LUAD) dataset revealed a lower proportion of M1 TAMs and a higher proportion of M2 TAMs in EGFR mutant tumors compared to those with wild-type EGFR." (PMID 39843434, 2025). "All of the identified co-occurring alterations in our study are well established based on data from previous studies, for example, the co-occurrence of PIK3CA, EGFR and KRAS in lung adenocarcinoma." (PMID 41153394, 2025). "Our histological assessment identified EGFR and KRAS as predominant driver genes, consistent with a report showing at least eight pathological subtypes in lung adenocarcinoma." (PMID 40502411, 2025). "A 60-year-old woman was diagnosed with lung adenocarcinoma (cT1cN3M0, cStage IIIB) harboring an EGFR exon 19 deletion (L747-A750>P)." (PMID 40051929, 2025). "In lung adenocarcinoma, our previous study demonstrated that resistin promotes metastasis via the TLR4/Src/EGFR/PI3K/NF-κB signaling pathway." (PMID 40002704, 2025). "In lung adenocarcinomas, des-Arg53-EGF binds to the EGF receptor (EGFR), and the tissue expression of CPM has been negatively correlated with disease survival." (PMID 40136513, 2025). "Resistin leads to lung adenocarcinoma cell migration and invasion through the TLR4/Src/EGFR/PI3K/NF‐κB pathway." (PMID 40040878, 2025). "AQP5 has been shown to activate EGFR and consequently to induce the MAPK signaling pathway in several types of cancer, such as glioma, lung adenocarcinoma, colon cancer, and also pancreatic cancer." (PMID 40305202, 2025). "Among the hotspot amplifications were the regions encompassing EGFR (ch7p11),KRAS (ch12p12), and MCL1 (ch1q21), which are well-recognized cancer drivers that play crucial roles and are known to be amplified in lung adenocarcinoma." (PMID 40867048, 2025). "At the time of progression to EGFR-targeted TKI therapy, histologic transformation in EGFR-mutant lung adenocarcinoma (LUAD) is observed in 5–15%." (PMID 41149474, 2025). "Lung adenocarcinoma cell lines HCC827 and PC-9 carrying an activating small in-frame deletion in exon 19 of EGFR (EGFR 19del) showed sensitivity to gefitinib." (PMID 39354638, 2024). "Based on PET/CT imaging combined with EGFR and PET metabolic indexes, established six machine learning models to predict brain metastases of lung adenocarcinoma." (PMID 38605303, 2024). "A possible mechanism involves EGFR activation of epithelial-mesenchymal transformation via protein kinases and STAT3 activation by leukocyte hormone-6 to promote brain metastasis in lung adenocarcinoma." (PMID 38605303, 2024). "The patient was a male diagnosed with lung adenocarcinoma (stage IIIA), who received first-generation EGFR-TKI (erlotinib) treatment for 60.1 months." (PMID 39456542, 2024). "Retrospectively collected 204 patients with lung adenocarcinoma who underwent PET/CT examination and EGFR gene detection before treatment from Cancer Hospital Affiliated to Shandong First Medical University in 2020." (PMID 38605303, 2024).